LINC00558 (long independently transcribed non-coding RNA 558)
Gene: Long non-coding RNA gene on chromosome 13 (53,815,419 to 53,939,960, forward strand). Ensembl gene ENSG00000261517.
Diseases named in the same sentence as LINC00558 in open-access papers:
LINC00558 is named in the same sentence as 1 disease in open-access papers, as found by Europe PMC text mining. Sharing a sentence is not in itself a finding about the gene and the disease. The quoted sentences say what the papers report.
fibromyalgia (1 paper, 2023). A chronic disorder of unknown etiology characterized by pain, stiffness, and tenderness in the muscles of neck, shoulders, back, hips, arms, and legs. "Several genes/loci have been reported more than once in CWP, fibromyalgia, and MCP, including EXD3, SLC39A8, AMIGO3/GMPPB/RNF123, C6orf106, FAF1, SLC24A3, and LINC01065/LINC00558." (PMID 37144689, 2023).